CBS (cystathionine beta-synthase)
Diseases named in the same sentence as CBS in open-access papers (continued):
Sharing a sentence is not in itself a finding about the gene and the disease.
cancer (continued). "Certainly, a greater appreciation for the complexity of CBS in cancer biology will give rise to new prospective biomarkers or targets for cancer." (PMID 30050925, 2018). "On the contrary, tumor-suppressive effects of CBS have been reported in other cancer types, suggesting context-dependent roles of CBS in tumor growth and progression." (PMID 30050925, 2018). "Malfunction of CBS can lead to pathologic conditions like cancer, cardiovascular and neurodegenerative disorders." (PMID 29410458, 2018). "CBS downregulation reduced antioxidant capacity and enhanced the sensitivity of cancer cells to chemotherapeutic drugs." (PMID 30050925, 2018). "The distinct biological effects of CBS alterations in different cancer models reveal the complexity of CBS signaling in cancer pathogenesis." (PMID 30050925, 2018). "It is now becoming clear that CBS activity also plays an important but complex role in cancer biology." (PMID 30050925, 2018). "The contradictory role of CBS in cancer biology is possibly due to the existence of alternative Hcy and H2S metabolic pathways, and multiple modes of regulation of CBS expression and activity by hormones, growth factors, and other metabolites." (PMID 30050925, 2018). "Increased understanding of the role of the CBS-controlled network in cancer biology will greatly promote the development of pharmacological reagents targeting CBS and the identification of appropriate patient populations." (PMID 30050925, 2018). "And CBS is one key regulatory enzyme in folate metabolism and plays an important role in promoting cellular bioenergetics, proliferation, and migration of cancer cells." (PMID 28881655, 2017). "CBS, in particular, has been shown to be overexpressed in colorectal, ovarian, and breast cancer, among other cancer types, as well as in neurodegenerative diseases, such as amyotrophic lateral sclerosis." (PMID 28421128, 2017). "Taking into account the important role of CBS-derived H2S in tumor growth and proliferation it is evident that a fine regulation of CBS levels is required to prevent cancer as well as in response to chemotherapy." (PMID 27385096, 2016). "Based on its roles in homocysteine homeostasis and H2S and glutathione generation, altered CBS activity/expression contributes to numerous diseases, including cancer." (PMID 27472325, 2016). "This function of CBS also involved mitochondrial localization of CBS and affected the ATP production and redox states, though role of CBS in lipid metabolism in cancer is still unexplored." (PMID 26452259, 2015). "Taken together the role of CBS in regulation of SREBPs, introduces CBS as an important player to the field of lipid metabolism in cancer." (PMID 26452259, 2015). "In selected cancer cell lines lipolysis is, therefore, an additional pathway for FA acquisition and our data suggest CBS regulates lipid uptake from its surroundings." (PMID 26452259, 2015). "Cancer cells, which are treated with H2S donor, NaHS, and cancer cells, which recover from damage, show an increased CBS and CTH driven H2S synthesis, and increased Nampt, the rate-limiting factor in NAD+ biosynthesis, and its product NAD+." (PMID 25248148, 2014). "As compared to parental undamaged Pc cells, cancer cells recovered from damage had increased CBS and CTH proteins in direct correlation with the recovery period." (PMID 25248148, 2014). "CBS co-localizes with mitochondrial markers in cancer cells, and silencing CBS decreases mitochondrial oxygen consumption with a concomitant increase in reactive oxygen species (ROS) production." (PMID 24236104, 2013). "Proliferative capacity of the cancer cells was also determined through Ki-67 staining, which showed significant reduction in the number of proliferating cancer cells with CBS knockdown alone." (PMID 24236104, 2013). "In cancer cells, CBS colocalizes with mitochondrial markers." (PMID 40442106, 2025).
cancer (continued). "Similar to AOAA, benserazide inhibits CBS through a PLP-dependent mechanism and in various cancer models, and produces the type of responses that would be expected from a CBS inhibitor in vitro and in vivo — although the required concentrations/doses are fairly high." (PMID 40187942, 2025). "In gastric cancers or other cancers dependent on PI3K/Akt signaling, CBS is often epigenetically silenced or downregulated, thus preventing cells from senescence maintenance and regaining the proliferative capacity to drive cancer development." (PMID 40227215, 2025). "Elevated H2S levels, alongside increased CBS expression, have been identified in numerous cancers." (PMID 39062461, 2024). "•Ablation of CBS enhances ferroptosis-based cancer therapies for CRC." (PMID 38490069, 2024). "CBS is an exciting therapeutic target because it regulates cancer cell survival." (PMID 38172561, 2024). "This is a significant observation that warrants further investigation because it may indicate that overexpression of CBS and/or CTH is closely associated with the pathogenesis of cancer." (PMID 39062461, 2024). "This suggests that CBS plays an important role in the progression of various types of cancer." (PMID 38828455, 2024). "The finding that cancer cells have reduced CBS anabolism compared to that in CAFs and normal pancreatic cells suggests that the exocrine cysteine produced by CAFs has a major role in maintaining metabolic activity in the cysteine/cystine-starved pancreatic milieu." (PMID 38389839, 2024). "Low basal levels of CBS may be important for cancer cells since CBS regulates cellular stress response." (PMID 38172561, 2024). "The expressions of xCT were higher in cancer cells than in normal cells, whereas the expressions of enzymes responsible for de novo cysteine synthesis, cystathionine-β-synthase (CBS), and cystathionine-γ-lyase (CTH), were lower in cancer cells than in healthy hepatocytes." (PMID 39413876, 2024). "Intriguingly, several complex factors influence the function of CBS in cancer." (PMID 39062461, 2024). "Therefore, future strategies to treat cancer patients should involve modulation of CBS and H2S levels." (PMID 37627515, 2023). "But in the human hepatoma cell line HepG2, inhibiting CBS results in cancer suppression." (PMID 36929586, 2023). "However, contradictory findings have been reported in different cancers, indicating a cancer type-dependent role of CBS." (PMID 38022516, 2023). "Among these enzymes, CBS is the most well studied in the cancer context." (PMID 38247476, 2023). "CBS targeting sensitizes cancer cells to conventional therapy and induces cell death." (PMID 38247476, 2023). "Cystathionine β-synthase (CBS) is a mammalian enzyme that transfers sulfur, promoting the conversion of homocysteine to cysteine, and produces hydrogen sulfide (H2S), which plays a supportive role in maintaining tumor cell proliferation and survival in cancers with high CBS expression." (PMID 37283791, 2023). "The translocation of CBS to mitochondria may have important implications for the regulation of cancer cell bioenergy and survival." (PMID 36558139, 2022). "Tumors with higher-grade cancers and serous histology contain higher levels of CBS." (PMID 35684331, 2022). "Based on Ki-67 staining, CBS silencing decreased cancer cell proliferation." (PMID 35684331, 2022). "Cancer cells express high levels of CBS and CTH and their genetic or pharmacological inhibition leads to a reduction in tumor vasculature, suggesting that the TSP metabolic reprogramming may be a promising therapeutic strategy for solid tumors." (PMID 35681715, 2022). "Considering the dichotomous effect of H2S and the development of new era H2S donors, our study set out to investigate the declining part of the bell and hypothesize that overexpression of CBS/H2S might exhibit an anti-cancer activity on CRC cells." (PMID 35172821, 2022). "A study using HCT116 cancer cells revealed that CBS is present in cytosol and mitochondria." (PMID 35684331, 2022).
cancer (continued). "CBS levels are typically higher in tumors with serous histology and a higher degree of cancer." (PMID 35684331, 2022). "Upregulation of hydrogen sulfide (H2S) biosynthesis, at least in part related to the upregulation of cystathionine β-synthetase (CBS) in cancer cells, serves as a tumor-promoting factor and has emerged as a possible molecular target for antitumor drug development." (PMID 34439739, 2021). "CSE, CBS, and 3MST, the three H2S-producing enzymes, are expressed in several types of cancer." (PMID 34944543, 2021). "This enigmatic role of H2S is interesting in relation to the development of innovative CBS inhibitors, H2S donors, and H2S-releasing hybrids that could therefore have potential for cancer therapy." (PMID 34944543, 2021). "Given this growing body of experimental and clinical evidence for the role of H2S as a pro-cancer bioenergetic, proliferative, and survival factor, we have pursued the development of novel inhibitors of cancer cell CBS activity as potential future anti-cancer therapies." (PMID 34439739, 2021). "For instance, in many cancer cells, CBS up-regulation produces elevated H2S levels, which the cancer cells use to drive their accelerated metabolism and proliferation and as a protective mechanism against anticancer therapies and perhaps against elimination by the host immune system." (PMID 32365821, 2020). "CBS silencing also affects the interaction of cancer cells with their microenvironment." (PMID 32365821, 2020). "Decreased expression of CBS and MTHFR has been associated with increased levels of homocysteine in breast, which might also increase the risk of cancer." (PMID 32078659, 2020). "Taken together, CBS overexpression significantly contributes to the pathogenesis of various cancer cells, and CBS silencing (on its own, or in combination with chemotherapeutic agents or immunotherapy) can exert significant antitumor effects in vitro and in vivo." (PMID 32365821, 2020). "The question whether CBS is regulated as cancer cells assume a more aggressive phenotype has been explored by several investigations." (PMID 32365821, 2020). "This review focuses on the current understanding of the functional role of CBS and the derived metabolites Hcy and H2S in cancer pathogenesis and provides insight into the development of novel prognostic markers and therapeutic approaches for cancer patients." (PMID 30050925, 2018). "Here, we review the physiological functions of CBS, summarize the complexities regarding CBS research in oncology, and discuss the potential of CBS and its key metabolites, including homocysteine and H2S, as potential biomarkers for cancer diagnosis or therapeutic targets for cancer treatment." (PMID 30050925, 2018). "It was shown that aberrant function of CBS may thus lead to cancer, cardiovascular and neurodegenerative diseases making it an interesting drug target." (PMID 29410458, 2018). "Therefore, the functional role of CBS is determined by the distinct metabolic and genetic profiles in different types of cancer and is context-dependent." (PMID 30050925, 2018). "CO inhibition of CBS in various cancer cells has been shown to affect the methylation state of 6-phosphofructo-2-kinase/fructose-2,6-biphosphatase 3 (PFKFB3), suppressing 6-phosphofructo-2-kinase, resulting in a shift of glucose from glycolysis to the pentose phosphate pathway." (PMID 30050658, 2018). "Therefore, more work in multiple experiment models is required to better define the role of SAM/CBS axis in cancer pathogenesis." (PMID 30050925, 2018). "In addition, cfDNA hypomethylation of CBS promoter in plasma was shown to be an independent prognostic factor for recurrence and cancer-related death in CRC." (PMID 28881655, 2017). "CBS also has a relevant role in human physiology by being a major source of H2S, a key endogenous signaling molecule whose dysregulation is at the basis of several human pathologies, from cardiovascular and neurodegenerative diseases to cancer." (PMID 28421128, 2017).
cancer (continued). "A plausible hypothesis is that CBS up-regulation observed in human tumor tissues and cancer cells could be a consequence of local or systemic inflammation." (PMID 27924828, 2016). "We speculate that cancer cells might exploit similar mechanisms for metabolic rewiring and chemoresistance by involving CBS." (PMID 26452259, 2015). "Hence, cancer-selective disruption of the lipid metabolism pathway is possible by targeting CBS and, at least for OC, promises a profound benefit." (PMID 26452259, 2015). "All of these data support a protective/survival role for CBS in cancer cells." (PMID 24236104, 2013). "The present study defines an important role for CBS in maintaining cancer cell health." (PMID 24236104, 2013). "Considering the remarkable cytoprotective action of physiological H2S and glutathione we posited that cancer cells might exploit this unique feature of CBS to produce H2S when under oxidative stress or upon cytotoxic insult." (PMID 24236104, 2013). "We found that the methylation-mediated silencing of CBS could be reversed by genetic or pharmacologic demethylation, suggesting that CBS functions as a tumor suppressor in these cancer types." (PMID 23152928, 2012). "CBS may promote cancer cell survival by increasing their internal antioxidant capacity." (PMID 41154707, 2025). "Consequently, the targeted inhibition of CBS could emerge as a promising therapeutic approach for cancer intervention." (PMID 38828455, 2024). "Despite the central role of CBS in the transsulfuration pathway and metabolism of sulfur-containing amino acids under physiological conditions, the regulation of CBS in cancer cells, which are under ferroptotic stress due to nutrient deprivation, remains unknown." (PMID 38490069, 2024). "Consequently, the selective inhibition of CBS could represent a promising therapeutic strategy for cancer." (PMID 38828455, 2024). "Interestingly, persister cancer cells show high consumption of methionine, thus suggesting that the transsulfuration pathway is mobilized, and a vicious cycle is generated through the CBS-H2S axis." (PMID 37381723, 2023). "AOAA, a CBS inhibitor, could suppress the development of different types of cancer." (PMID 35795862, 2022). "Therefore, modulation of the CBS and H2S levels could help limit cancer proliferation and promote its reversal." (PMID 30804341, 2019). "Importantly, we found the inhibition of CBS could lead to ferroptotic cancer cell death and the new CBS inhibitor effectively reduces the tumor growth in a liver tumor xenograft mice model." (PMID 30258181, 2018). "Thus, the suppression of CBS by promoter methylation, instead of genetic alterations, would also result in a disturbance of methyl-group metabolism and contribute to cancer development with increased DNA damage by oxidative stress, impairing antioxidant capacity, and dysregulating DNA methylation." (PMID 23152928, 2012). "Another line of studies demonstrates that H2S, generated by CBS, or 3-MST also plays a pathogenetic role in several types of cancer." (PMID 40187942, 2025). "Taken together, these results support the possibility of utilizing CBS, CSE and 3-MST as potential molecular targets for cancer treatment." (PMID 38250807, 2024). "While the regulation of CBS, CSE, 3-MST (and to a lesser degree CARS2) in various forms of cancer has been studied intensively, the regulation of the various H2S degradation pathways remains to be investigated." (PMID 39643979, 2024). "In contrast to CBS, cellular cystathionine gamma cleavage enzyme (CTH) expression is upregulated in a wide variety of cancer types, including HCC, while endogenous inhibition, which exerts one of its anticancer effects, has also been demonstrated." (PMID 37895865, 2023). "Increased expression of 3-MST along with CBS and CSE was reported in renal cell carcinomas and was established by a study conducted using 88 human kidney tissue specimens from healthy and cancer patients." (PMID 36978851, 2023).
cancer (continued). "Cystathionine beta-synthase (CBS) is the first rate-limiting enzyme in the transsulfuration pathway and play vital roles in the occurrence, development, and treatment of cancer." (PMID 37147729, 2023). "Hydrogen sulfide is also produced through cystathionine beta-synthase and cystathionine gamma-lyase, along with 3-MST, and is known to alleviate a variety of illnesses such as cancer, heart disease, and neurological conditions." (PMID 36978851, 2023). "We then identified the involvement of CD44 in the effect of CBS/H2S axis on CRC cells, which is a well-known transmembrane marker for its pro-cancer and stemness-maintenance function." (PMID 35172821, 2022). "CBS silencing and pharmacological inhibition of CTH in cancer cells, the major H2S producers, reduce tumor angiogenesis." (PMID 35681715, 2022). "Later on, several other studies reported on the upregulation of CBS, CSE, and 3-MST in various cancers." (PMID 35684331, 2022). "LINC00336 can also regulate cystathionine-β-synthase (CBS) by affecting microRNA 6852 (MIR6852), and CBS can trigger the ferroptosis process of cancer cells." (PMID 35784729, 2022). "Increased H2S synthesis and CBS, CSE, and/or 3-MST expression promote cancer progression in several human malignancies, and H2S synthesis inhibitors have been proposed as a cancer treatment." (PMID 34829691, 2021). "Over the subsequent seven years, these findings have been confirmed and extended to many different tumor types: it is now clear that CBS, and/or CSE and/or 3-MST is overexpressed in many forms of cancer." (PMID 33499368, 2021). "The roles of CBS and CSE in neoangiogenesis have been shown for different cancer types, and possibly involve per-sulphidation of KATP channels and the activation of MAPK signalling pathways, which have been demonstrated in endothelial cells." (PMID 33223534, 2021). "Cysteine degradation catalyzed by CAT and MST is not deeply explored in cancer, since MST is more enzymatically efficient at a pH higher than the physiological, thus the role of CBS and CSE is considered more relevant in cancer biology." (PMID 32714858, 2020). "The expression of CBS and CSE seems to be cancer type-related often dependent on the organ and the genetic background." (PMID 32714858, 2020). "We also determined the role of endogenous H2S in cancer cell viability by testing the effects of CSE inhibitor PPG and CBS inhibitor HA on the viability of SGC7901 cells." (PMID 26078811, 2015). "Other genes involved in one-carbon metabolism were found transcriptionally repressed in HCC tissue, although the methylation pattern was unchanged in BHMT1, BHMT2, CBS, GNMT, and MTHFD2L in cancer as compared to cancer-free tissue or decreased in FOLH1." (PMID 25945129, 2015). "Cancerous tissues of various types have shown higher CBS expression levels compared to surrounding non-cancerous tissues, although in some malignant tissues, CBS expression was found to be lower than in corresponding non-cancerous tissues." (PMID 41373571, 2025). "Within cancer cells, apart from the xCT transporter's role in promoting selenium metabolism, there are several enzymes that influence the selenium metabolism pathway, including SEPHS2, CSE, and CBS." (PMID 41323827, 2025). "Cancerous tissues of the colon, prostate, ovary, kidney, and BC have shown higher expression levels of CBS than surrounding noncancerous tissues." (PMID 39643979, 2024). "However, cysteine deprivation was shown to increase the dependency of cancer cells on the activity of CBS42, and CBS has been shown to promote ovarian and colon cancer." (PMID 38172561, 2024). "Activation of NRF2 axis in cancer cells triggers the induction of multiple anti-ferroptotic genes, including SLC7A11, ATP binding cassette subfamily C member 5 (ABCC5), metallothionein 1G (MT1G), FSP1, CBS, and superoxide dismutase 2 (SOD2)." (PMID 39624080, 2024).